ADAM17 (ADAM metallopeptidase domain 17)
Diseases named in the same sentence as ADAM17 in open-access papers (continued):
Sharing a sentence is not in itself a finding about the gene and the disease.
tumor (continued). "2-Deoxy-D-glucose and siRNA suppresses the activation of ADAM10 and ADAM17, down-regulates mesenchymal properties, reduces the secretion of EMT-associated cytokine, and renders the tumor susceptible to anti-cancer drug treatment." (PMID 34502094, 2021). "Some miRNAs are mainly expressed as tumor suppressors, and ADAM17 were proved to be the direct target of miRNAs." (PMID 34182543, 2021). "TNF-α is produced by tumor cells in abundance promoting cell survival in an NF-κB-dependent mechanism suggesting the crucial role of ADAM-17 and MMPs in promoting tumorigenesis." (PMID 34912809, 2021). "IR strongly enhanced tumor cell–associated ADAM17 activity, released VEGF in an ADAM17-dependent manner, and thereby coordinated the communication between tumor and endothelial cells." (PMID 36860547, 2021). "Overall, these complementary experiments demonstrate irradiation-induced shedding of ADAM17 substrates from tumor cells, which increase migration of endothelial cells in trans." (PMID 36860547, 2021). "CD24 expression in HCC has also been associated with iNOS-induced TACE/ADAM17-dependent activation of Notch1, which is linked to tumor progression and stemness." (PMID 32183251, 2020). "In this case, high activity of TACE/ADAM-17 in DCs can also promote tumor growth via inhibition of the cytotoxic DC activity by way of decreasing mTNFα levels." (PMID 32326230, 2020). "Expression analysis of intestinal epithelial cells showed that ADAM17 was highly upregulated on tumor tissue while the mIL-6R was strongly downregulated." (PMID 32867390, 2020). "ADAM17 is related to inflammation and cancers, participates in the tumor proliferation and invasion, and processes more than 80 substrates." (PMID 32610677, 2020). "Binding of PP2A‐B56 to ADAM17 protease decreases growth factor signaling and tumor development in mice." (PMID 32400009, 2020). "ADAM17 was also shown to be overexpressed in gastrointestinal stroma tumours (GIST) where it co-localised with EGF and EGFR." (PMID 32698506, 2020). "Numerous studies have confirmed that ADAMs, especially ADAM17, play a major role in modulating tumor growth and metastasis through regulating cell signaling pathways." (PMID 33260349, 2020). "A recent study has found that both the activation of EGF-R pathways, as well as IL-6 trans signaling can be observed during tumor development, and both require ADAM17." (PMID 33143292, 2020). "This also suggests a potential critical role of ADAM17 on tumour or stroma cells to provide EGFR ligands." (PMID 32698506, 2020). "In this regard, the ADAM17 prodomain has been identified as a potent inhibitor of ADAM17 surface activity, which significantly reduced tumour burden in LAC models." (PMID 31438559, 2019). "Both CD16A and CD16B are cleaved rapidly on neutrophil and NK cell activation after mitogen stimulation and co-culturing with tumor targets and the cleavage is mediated by a metalloprotease, ADAM17 (a disintegrin and metallopeptidase domain 17)." (PMID 30805309, 2019). "Along the same line, pharmacologic inhibition of ADAM17 activity also led to decreased tumor formation in KrasG12D mice together with decreased sIL-6R levels." (PMID 31694340, 2019). "The authors showed that the stimulation of ADAM17 expression by severe hypoxia in several tumour cell lines occurs as a consequence of the activation of the PERK/eIF2α/ATF4 pathway and activating transcription factor 6 (ATF6)." (PMID 30709842, 2019). "Hence, it is actually unknown if the here analyzed ADAM17 mutations are actively driving tumorigenesis (‘driver mutation’) or if another mutation, e.g., within the oncogene KRAS gene is primarily involved in tumor formation and variants within ADAM17 are found as a so-called ‘passenger mutations’." (PMID 31060243, 2019). "Collectively, these data strongly support the notion that ADAM17 promotes KrasG12D‐dependent LAC by supporting tumor cell proliferation and inflammation." (PMID 30833304, 2019).
tumor (continued). "Using these preclinical model systems, the specific genetic and therapeutic targeting of ADAM17, the latter with a non‐toxic prodomain inhibitor, suppressed tumor burden by reducing cellular proliferation in tumors." (PMID 30833304, 2019). "In genetically engineered and xenograft (human cell line and patient‐derived) KrasG12D‐driven LAC models, the specific blockade of ADAM17, including with a non‐toxic prodomain inhibitor, suppressed tumor burden by reducing cellular proliferation." (PMID 30833304, 2019). "Although ADAM17 is often overexpressed in tumours and at sites of inflammation, little is known about the regulation of its expression." (PMID 30709842, 2019). "Kaplan-Meier analysis revealed that T stage, regional lymph node metastasis, residual tumor, ADAM-10, ADAM-17, and ADAM-28 were associated with shorter time to tumor progression/recurrence (TTP)." (PMID 29776401, 2018). "As for overall survival, T stage, regional lymph node metastasis, residual tumor, ADAM-10, and ADAM-17 were associated with decreased overall survival for patients with HC." (PMID 29776401, 2018). "In the present study, we confirmed that FoxM1 regulated ADAM-17 expression in vivo and in vitro, leading to enhanced cell proliferation and tumor growth." (PMID 29776401, 2018). "The upregulation of FoxM1 and ADAM-17 led to an increase in the activities of cell proliferation and tumor growth, as well as TNFa expression and cleavage, whereas the downregulation of FoxM1 and ADAM-17 showed the opposite results." (PMID 29776401, 2018). "Further analysis showed a significant correlation between ADAM-10 overexpression and T stage (P = 0.009) and AJCC TNM stage (P = 0.007), ADAM-17 and larger tumor size (P = 0.007) and AJCC TNM stage (P = 0.002), ADAM-28 and AJCC TNM stage (P = 0.027)." (PMID 29776401, 2018). "As a member of the ADAM family of metalloproteases, ADAM‐17 involves in cell adhesion, migration, cellular signalling and proteolysis, recently emerging as a potential therapeutic target in several tumour types." (PMID 29956475, 2018). "A decrease in the expression of ADAM-17 by silencing FoxM1 led to an inhibition of cell proliferation, tumor growth, and the production of tumor necrosis factor α." (PMID 29776401, 2018). "To validate the additive effect of ADAM17 blockage and cisplatin treatment in primary cells, we used patient-derived cells from tumor tissue (Pat.T1) and ascites-derived cells (Pat.As.4 and Pat.As.5), shown as examples due to restriction of primary material." (PMID 29662625, 2018). "The mice in FoxM1 + sh-EGFP group were thinner than those in FoxM1 + sh-ADAM17 group 20 days after implanting the tumor." (PMID 29700308, 2018). "In the current study, ADAM17 knockdown in SW1783-FoxM1 cells dramatically impeded the tumor growth and increased the biologic status and survival of mice." (PMID 29700308, 2018). "An ADAM17 inhibitor, because of its substrate profile, has so many ways in which to inhibit tumor proliferation." (PMID 29230082, 2017). "Again, it is unclear how targeting IL23R shedding via inhibition of ADAM17 would promote tumor inflammatory processes." (PMID 29230082, 2017). "The function of ADAM17 in tumor immunosurveillance is quite complex and there is a contradictory role for ADAM17 inhibitors to be used for cancer immunotherapy due to the enzyme's substrate profile." (PMID 29230082, 2017). "More recently, substrates for ADAM17 have included molecules that are important for tumor immunosurveillance and studying of shedding events orchestrated by this enzyme has led to proposed novel mechanisms of resistance to popular cancer therapies." (PMID 29230082, 2017). "This suggests that ADAM10 and ADAM17 are important components of the tumourigenic niche which function to retain cancer stem cells in this niche, promoting self-renewal and tumour recurrence." (PMID 27541285, 2017).
tumor (continued). "Based on our findings, we propose that ADAM17- regulated inflammatory mediators, such as Cox-2, are important promoters of tumor formation." (PMID 27738494, 2016). "The high expression of ADAM17 genes is poor prognostic factor in various cancer types and correlates with tumor progression (e.g., breast, prostate, gastric, colorectal, hepatocellular, and ovarian cancer)." (PMID 27110571, 2016). "ADAM17 promotes tumor-induced angiogenesis through upregulation of growth factors such as VEGF via MAP kinase activation." (PMID 26993601, 2016). "Our findings demonstrate that high levels of ADAM17 expression are found on leukocytes located within the tumor microenvironment." (PMID 27738494, 2016). "While low levels of ADAM17 staining were observed on tumor cells, higher levels of staining were observed on a number of K8-negative cells." (PMID 27738494, 2016). "Low levels of PTEN and high levels of ADAM17 in tumours correlated with high tumour grading (P<0.0001) and Gleason score (P<0.0001)." (PMID 27941799, 2016). "Analysis of co-staining revealed that approximately 47% of CD45+ leukocytes within the tumor express detectable levels of ADAM17 (arrow)." (PMID 27738494, 2016). "Together, these studies reveal novel functions for ADAM17 in the regulation of macrophage function in the microenvironment during tumor formation." (PMID 27738494, 2016). "Metalloproteinases ADAM-10 and ADAM-17, which cleave membrane CXCL16 to generate soluble CXCL16, have also been linked to increased tumor burden." (PMID 27471636, 2016). "ADAM17, a sheddase for numerous growth factors, cytokines, receptors, and cell adhesion molecules, is believed to promote tumor development, facilitating both tumor cell proliferation and migration, as well as tumor angiogenesis." (PMID 26176220, 2015). "Although the targeting of ADAM17 is considered a promising strategy in tumor therapy, its role in tumor cell dissemination into lymphatic vessels, as well as its effect on lymphatic endothelial cells in general, has not yet been explored." (PMID 26176220, 2015). "Previous studies found that selective inhibitors of ADAM17 protease can block the tumor cell EGFR pathway." (PMID 25351873, 2015). "In various in vitro models ADAM17 has been shown to potentiate cell proliferation, especially in the case of tumor cells that exhibit autocrine growth stimulation due to the simultaneous expression of EGFR family of growth factor receptors and their ligands." (PMID 26176220, 2015). "A disintegrin and metalloproteinase-17 (ADAM17) has been shown to regulate numerous proteins involved in the cell cycle, as well as tumor oncogenes." (PMID 25364437, 2014). "The top two networks have been merged to obtain a global view of the proteins that were differentially regulated between the tumor tissues: control and overexpressing ADAM-17." (PMID 24495306, 2014). "Among them, 110 proteins were down-regulated and 90 were up-regulated in tumor tissues overexpressing ADAM17." (PMID 24495306, 2014). "ADAM17, a member of the ADAM gene family, has been shown to be highly expressed in various human tumors, reflecting the degree of malignancy, since ADAM17 promotes tumor invasion and metastasis." (PMID 25364437, 2014). "An orthotopic murine tumor formation model using SCC-9 cells overexpressing ADAM17 or GFP was performed." (PMID 24495306, 2014). "We next performed statistical analysis to explore global proteomic difference between tumor overexpressing ADAM17 and control tumor samples." (PMID 24495306, 2014). "To confirm the expression of Adam17 and IL-6Rα by MDSCs in vivo, we analyzed spleen tissues, primary tumor masses and metastatic lesions in the lungs from 4T1 cell-bearing mice." (PMID 24021059, 2013). "ADAM-17 was highly expressed as the tumor stage increased, in the stageI, only 3/14 tissues were ADAM-17 positive but in the stage III and IV, the ADAM-17 positive tissue were increased to 21/25 and 5/6." (PMID 23659326, 2013).
tumor (continued). "We therefore analyzed the constitutive and inducible surface expression of ADAM10 and ADAM17 on a variety of human T cell and tumor cell lines." (PMID 24130797, 2013). "Confocal microscopy showed that MDSCs in the spleen, primary tumor sites and lung expressed increased levels of Adam17 and IL-6Rα on their surfaces in 4T1 cell-bearing mice compared to those in EMT6 cell-bearing mice." (PMID 24021059, 2013). "Of the tumors that did develop in mice injected with the HNSCC cells with stably suppressed levels of ADAM17, the mean tumor volume was only 29.8 mm3, whereas the tumors in mice injected with control transduced cells reached a mean tumor volume of 117.8 mm3." (PMID 24403253, 2013). "Injection of HNSCC cells with stably suppressed levels of ADAM17 led to significantly reduced tumor volumes and incidence." (PMID 24403253, 2013). "The data showed that the primary and metastatic tumor samples exhibited increased levels of ADAM17 expression and concomitant CD44 cleavage compared to normal controls." (PMID 24403253, 2013). "The major mechanism by which ADAM17 contributes to tumor progression was proposed to involve the activation of growth factor receptors of EGFR (ErbB/HER) family." (PMID 23251384, 2012). "It is generally accepted that ADAM17 promotes tumor development via activating growth factors from the EGF family, thus facilitating autocrine stimulation of tumor cell proliferation and migration." (PMID 23251384, 2012). "The main difference between mock-transfected and ADAM17-silenced tumors, visible to the naked eye, was the density and organization of blood vessels on the tumor surface and in the dermis surrounding the tumors." (PMID 23251384, 2012). "The ADAM-17 inhibitor INCB7839 has been shown to partially inhibit tumor cell growth at concentrations over 10 μM and synergized with targeted and cytotoxic drugs." (PMID 23028451, 2012). "The aim of this study was to evaluate the pharmacokinetics, pharmacodynamics and anti-tumour efficacy of the first specific inhibitor, an anti-human ADAM17 IgG antibody, clone D1(A12)." (PMID 22792380, 2012). "In those models, expression of ADAM17 positively correlated with in vivo tumor progression and in vitro proliferation rate of tumor cells in serum-free medium." (PMID 23251384, 2012). "We have excluded the possibility that ADAM17 contributes to MC38CEA tumor progression via shedding of the ligands for EGFR and ErbB4." (PMID 23251384, 2012). "In some tumor models ADAM17 was shown to support autocrine stimulation of cell growth by shedding EGF family members." (PMID 23251384, 2012). "Among the growth factors susceptible to shedding by ADAM17, neuregulin-1 was the only candidate to mediate the effects of ADAM17 on MC38CEA motility and tumor angiogenesis." (PMID 23251384, 2012). "Disruption of the ALCAM-mediated adhesiveness by proteolytic sheddases such as ADAM17 has been suggested to have a relevant impact on tumour invasion." (PMID 19603023, 2009). "ADAM17 (A Disintegrin and Metalloproteinase-17) also called TACE (TNF-alpha converting enzyme) plays a pivotal role in the processing of numerous growth factor proteins, and has emerged as a new therapeutic target in several tumor types." (PMID 19772640, 2009). "Previously, we have reported that increased ADAM17 expression and protease activity contributes to hypoxic-induced tumor invasion." (PMID 19772640, 2009). "Recent studies showed that when ADAM17 is either inhibited or suppressed there is attenuation in tumor invasiveness and malignancy, resulting in a better outcome for breast cancer patients." (PMID 19772640, 2009). "Additionally, the correlation between the concentration of ADAM10 and ADAM17 in blood serum and tissue material collected from the tumor and the matched surgical margin in patients operated on for CRC was investigated." (PMID 39940871, 2025).
tumor (continued). "This might mean that the concentration of ADAM10 and ADAM17 directly in the tumor tissue and the surrounding tissue of the surgical margin is more closely correlated than with the concentration of these proteins in the serum." (PMID 39940871, 2025). "ADAM10 and ADAM17, especially, facilitate the shedding of critical developmental and growth factors and their receptors, as well as immuno-regulatory molecules, hence promoting tumour progression, immune escape, and resistance to therapy." (PMID 40427200, 2025). "Furthermore, antibody-based therapies targeting AREG or targeting AREG shedding by ADAM17 antibody have demonstrated anti-tumor efficacy in preclinical models." (PMID 40725192, 2025). "The analysis included ADAM10 and ADAM17 concentrations in the tumor tissue and matched surgical margin, as well as selected clinical and laboratory parameters, such as TNM stage according to the 8th edition, the presence of selected comorbidities and SIR parameters: NLR and PLR." (PMID 39940871, 2025). "However, it was shown that a higher concentration of ADAM10 and ADAM17 proteins in the tissue from the resection margin correlates with a higher concentration of ADAM10 and ADAM17 proteins in the tissue from the tumor." (PMID 39940871, 2025). "In addition, ADAM17 promotes chemotherapy resistance and tumor cell proliferation and survival by shedding EGFR ligands (e.g., Amphiregulin, AREG)." (PMID 41050403, 2025). "In another study, it was reported that, ADAM17 expression notably enhances in high-grade tumors in comparison with low-grade ones and did not relate to lymph node metastasis, estrogen receptor status, and tumor size." (PMID 38317965, 2024). "The transient or tumor-specific activity of ADAM10 or TACE/ADAM17 may play a key role because changing the mFKN/sFKN ratio modifies the signaling of the FKN/CX3CR1 axis to reveal anti- or pro-tumor effects." (PMID 38731899, 2024). "Given that ADAM17-mediated substrate cleavage is highly dependent on the biological context, the regulation of Lag-3 and Tim-3 by ADAM17 in tumor-infiltrating CD8+ T cells might have more complex mechanisms." (PMID 38918390, 2024). "Acquisition of an aggressive phenotype, as evidenced by enhanced motility or ability to invade, may be explained by increased ADAM17-mediated EGFR transactivation in such tumours." (PMID 38397010, 2024). "Hence, ADAM17 ablation in CD8+ T cells improved their anti-tumor activity in both TCR-T (OT-I) and CAR-T cell models." (PMID 38918390, 2024). "Notably, ADAM17 regulates the vascular endothelial cell barrier and promotes tumor growth, while VE-cadherin serves as a crucial adhesion protein that inhibits tumor hematogenous metastasis." (PMID 38413999, 2024). "A17α-MHCKO mice showed less cardiomyocyte apoptosis induced by doxorubicin than A17fl/fl mice, and cardiomyocyte ADAM17 deficiency did not affect the anti-tumor effect of doxorubicin." (PMID 39406701, 2024). "Additionally, there was a correlation between ADAM17 protein expression in oesophageal squamous cells and lymph node metastasis as well as the tumor stage (p < 0.05)." (PMID 38673838, 2024). "ADAM17 ablation enhanced the anti-tumor activity of CD8+ T cells." (PMID 38918390, 2024). "While intratumoral administration of low-dose sumIL-2 alone could effectively control the tumor growth, the combination of sumIL-2 treatment with ADAM17 ablation in T cells further enhanced the antitumor efficacy." (PMID 38918390, 2024). "Interestingly, KO/KD of either iRhom1 or iRhom2 decreases CD44 cleavage and further improves the CD44-mediated tumor targeting of NPs likely through decreasing the activity of ADAM17." (PMID 38177179, 2024). "Additionally, ADAM17 exhibits high expression in various tumor types, influencing tumor progression." (PMID 38413999, 2024). "Ki-67 staining revealed that ADAM17 knockdown decreased the proliferative ability of tumour cells." (PMID 38069391, 2023).